ANP32A (acidic nuclear phosphoprotein 32 family member A)
Diseases named in the same sentence as ANP32A in open-access papers (continued):
Sharing a sentence is not in itself a finding about the gene and the disease.
tumor (20 papers, 2010 to 2023). "Our data indicated that high expression of ANP32A was significantly associated with N stage and tumor differentiation status in OSCC patients." (PMID 26918356, 2016). "Based on previous literature, we have seen that ANP32a is a multifunctional protein involved in the regulation of many cellular processes, including tumor suppression, apoptosis, cell cycle progression, neuritogenesis and transcriptional regulation." (PMID 36555564, 2022). "To date, ANP32A has been reported to play roles in a variety of cellular functions, including RNA transport, transcription, cell-mediated cytotoxicity, and tumor suppression." (PMID 33823794, 2021). "Other observations have shown that the effect of miR-21 on tumor invasion can also take place by inhibiting tumor suppressor genes ANP32A, SMARCA4 and sprouty homolog 2 (Spry2)." (PMID 32349263, 2020). "In our eight mRNAsi based signature, high expression of RGS16, LYVE1, hnRNPC, ANP32A, and AIMP1 are correlated with a high risk of death as these genes focus in promoting cell proliferation and tumor progression, similar to stem cells." (PMID 33329703, 2020). "ANP32A was established as a tumor suppressor, able to activate the Apaf-1 apoptosome, and thereby inducing caspase-9 dependent apoptosis." (PMID 30890743, 2019). "ANP32A, also referred to as I1PP2A, acts as a tumour suppressor and ANP32C is oncogenic, with both aberrantly expressed in human malignancy." (PMID 31623614, 2019). "In HCC, acidic leucine-rich nuclear phosphoprotein 32 family member A (ANP32A) has been reported to promote tumor growth and to be a marker of poor prognosis." (PMID 28486557, 2017). "Conversely, Satb1, a key factor of chromatin remodeling and Anp32a, a tumor suppressor and inhibitor of histone acetyl-transferases, were repressed at the transcript level." (PMID 27602772, 2016). "Other highly enriched TFs that regulate proliferation and transformation (tumor supressors) are ANP32A and RUNX3." (PMID 25649207, 2014). "Mechanical study indicates that ANP32A promotes tumor cell growth and may involve the inactivation of p38 and phosphorylation of Akt." (PMID 33329703, 2020). "Likewise, a higher ANP32A expression was related to moderate/poor tumor differentiation in these two scoring systems (adjusted odds ratios, aOR = 2.2, P < 0.05, in both systems)." (PMID 26918356, 2016). "Our findings also showed that high ANP32A protein level was associated with a higher level of lymph node metastasis and tumor differentiation, but not with TM classification and tumor stage." (PMID 26918356, 2016). "In this prognostic signatures, high expression of RGS16, LYVE1, hnRNPC, ANP32A, and AIMP1 focus in promoting cell proliferation and tumor progression." (PMID 33329703, 2020). "Although ANP32A is now well established as a tumor suppressor and regulator of gene expression and proliferation, the exact function of ANP32B is still poorly understood, despite sharing 70% sequence identity and >80% sequence homology with ANP32A." (PMID 30890743, 2019). "ANP32A was observed in both nucleus and cytoplasm of OSCC cells and in non-tumor tissues." (PMID 26918356, 2016). "To study the prevalence of ANP32A in OSCC patients, at first we examined the expression pattern of ANP32A using immunohistochemistry on the tumor tissues and adjacent non-tumor tissues from 259 patients with OSCC." (PMID 26918356, 2016).
infection (18 papers, 2012 to 2026). The state of being infected such as from the introduction of a foreign agent such as serum, vaccine, antigenic substance or organism. "To confirm that infection of human cells with the avian-like WSN-K627E virus would be restored by avian ANP32A, we transiently expressed chicken ANP32A (chANP32A) in HEK-293T cells and infected the cells with either wild-type WSN or avian-like WSN-K627E virus." (PMID 34935435, 2022). "As our lab has an avowed interest in the biological roles of host RNA-binding proteins on viral RNA functions during infection, we focused our efforts on the host hnRNP K, hnRNP A1, and ANP32a proteins." (PMID 32841293, 2020). "Infection of ANP32A−/− and ANP32A+/+ mice with a seasonal H3N2 IAV or a highly pathogenic H5N1 human isolate did not result in any significant differences in virus tropism, innate immune response or disease outcome." (PMID 32231671, 2020). "To conclude, our study suggests that the host factor ANP32A incorporated into virus particles has a significant role in the support of viral replication in newly infected cells, especially in the process of interspecies infection of AIV." (PMID 38295177, 2024). "Avian ANP32A stimulates infection and replication of IAV containing PB2 627E." (PMID 34935435, 2022). "ANP32A is required for both cRNA and vRNA synthesis during infection." (PMID 34935435, 2022). "In order to verify the effect of swANP32A on the replication and infection of avian influenza virus in pig cells, we first constructed ANP32A knockout pig kidney epithelial PK15 (referred to as PK15-AKO) cell line by using CRISPR-Cas9 system targeting the second exon of the ANP32A gene." (PMID 32084248, 2020). "Altered expression of four genes, ATPase, Na+/K+ transporting, beta 1 polypeptide (Atp1b1), Growth hormone (Gh), acidic leucine-rich nuclear phosphoprotein 32 family member A (Anp32a) and Granulin (Grn) at the very early time of post-infection provided insights into the mechanism of pathogenesis." (PMID 23372423, 2012). "To this end, we established a competition-based NGS assay involving low multiplicity-of-infection (MOI) serial passaging of a defined mixture of rWSN-based PB2-627K and PB2-627E model viruses to determine which PB2 variant would be selected for by each ANP32A isoform." (PMID 31363119, 2019). "Reconstitution of dKO cells with both ANP32A and ANP32B proteins by transient transfection prior to infection restored PR8 virus replication." (PMID 31217244, 2019). "Taken together, these results imply that both ANP32A and ANP32B support infection in humans, but only ANP32A performs this role in chickens, with ANP32B being unable to help the polymerase." (PMID 31179971, 2019). "Because Stock-TKO virus established productive infection in HEK293T cells, we speculated that the reason is that endogenous human ANP32A/B (huANP32A/B) supports viral polymerase activity." (PMID 38295177, 2024). "Following infection, there was no increase in either vRNA or cRNA levels over time in the absence of ANP32A/B, confirming ANP32 proteins are essential for replication." (PMID 36645303, 2023). "Together these data indicate that even the entire deletion of chicken ANP32A is not sufficient to abrogate IAV mutant infections of chicken." (PMID 37816720, 2023). "Notably, almost all genes identified in this manner have elevated expression with MON‐DNJ across infection groups at 6 h with the exception of RPLP1 and ANP32A." (PMID 34287854, 2021). "To further determine whether the vRNA levels were regulated by ANP32A, we pre-expressed PB1, PB2 K627E or 627K, PA and NP as well as chANP32A-X1 or huANP32A in 293T cells for 24h before infection with PR8-PB2 K627E or PR8-PB2 627K virus (MOI = 5) and CHX-treatment for 4 h." (PMID 31608791, 2019).
infection (continued). "Nonetheless the significantly reduced level of virus replication observed in the chicken cells that lack chANP32A in vitro implies that in vivo, chickens that do not express ANP32A or express altered protein may be resilient to infection by IAV." (PMID 31159925, 2019).
cancer (10 papers, 2010 to 2024). A tumor composed of atypical neoplastic, often pleomorphic cells that invade other tissues. "High ANP32A expression was associated with high stage of lymphnode metastasis at cancer diagnosis, and the mortality hazard risk was multiplicatively enhanced among N2/N3 patients with high ANP32A expression." (PMID 26918356, 2016). "Acidic nuclear phosphoprotein 32 family member A (ANP32A), which regulates p38 and Akt activity to modulate cell growth in some cancers, mediates assembly of the IAV replicase." (PMID 38257829, 2024). "ANP32A also known as protein phosphatase 32 (PP32), is a type of nuclear phosphoprotein that is overexpressed in numerous cancers, including CRC9-11." (PMID 37781083, 2023). "It is worth noting that a previous study has shown that ANP32A plays a role in promoting cancer in HCC." (PMID 35280441, 2022). "The 8-mRNAsi based prognostic model in our signatures includes RGS16, LYVE1, hnRNPC, ANP32A, AIMP1, ZNF66, PIK3R3, and MAP2K7, in which several genes have been reported to be linked with stemness features or be involved in cancer progression." (PMID 33329703, 2020). "Acidic leucine-rich nuclear phosphoprotein-32A (ANP32A) is a multifunctional protein aberrantly expressed in various types of cancers." (PMID 26918356, 2016). "Our findings suggest that ANP32A expression increases as cancer cells progress toward malignant phenotype." (PMID 26918356, 2016). "From our study it is evident that, Allred and IRS can be used as a golden standard system to evaluate ANP32A expression in various other cancers." (PMID 26918356, 2016). "pp32 (ANP32A) has a unique pattern of expression in many human cancers." (PMID 21152064, 2010). "Members of the acidic leucine-rich nucleophosphoprotein 32 (ANP32) family, which mainly includes ANP32A, ANP32B, and ANP32E, are abnormally expressed and have prognostic value in certain cancers." (PMID 35280441, 2022). "Anp32a codes for a protein that has been found to be decreased or absent in malignant tumors, and to modulate cell growth by regulating p38 and AKT activity." (PMID 35267932, 2022). "PHAP1 (Putative HLA‐DR‐associated protein 1), also termed acidic leucine‐rich nuclear phosphoprotein 32A (ANP32A), Phosphoprotein 32 (pp32) or protein phosphatase 2A inhibitor (I1PP2A), is a multifunctional protein aberrantly expressed in multiple types of human cancers." (PMID 29667783, 2018).
nervous system disease (2 papers, 2015 to 2021). "The regulation of ANP32A signaling might help control oxidative stress in the brain and recover cognitive function, perhaps with therapeutic applications for neurological diseases." (PMID 34746237, 2021).
neurodegenerative disease (2 papers, 2017 to 2023). A disorder of the central nervous system characterized by gradual and progressive loss of neural tissue and neurologic function. "ANP32A is a multifunctional protein that participates in cell apoptosis, tumorigenesis, and neurodegenerative diseases." (PMID 37781083, 2023).
cardiac disease (1 paper, 2025). "Western diet also downregulated ANP32A (Acidic Nuclear Phosphoprotein 32 Family Member A), a translational repressor of the Wnt pathway known to impact cardiac disease." (PMID 40709334, 2025).
CNS tumors (1 paper, 2016). "MiR-21 is upregulated in a variety of CNS tumors, possibly because of its role in targeting tumor suppressors Acidic Nuclear Phosphoprotein 32 Family, Member A (ANP32A) and SWI/SNF-related, Matrix-associated, Actin-dependent Regulator Chromatin group A (SMARCA4)." (PMID 26904099, 2016).
ANP32A also shares sentences with these, for which no sentence is quoted: hepatocellular carcinoma (4 papers); acute myeloid leukemia (3); cognitive deficits (3); B-cell lymphoma (2); colon cancer (2); lung carcinoma (2); memory impairment (2); prostate carcinoma (2); T cell Lymphoma (2); acute megakaryoblastic leukemia (1); adenocarcinoma (1); brain tumours (1); cognitive (1); hematological malignancies (1); lymphoma (1); osteoarthritis (1); osteosarcoma (1); spinal cord injury (1); squamous cell carcinoma (1); virus infection (1).